PON1 (paraoxonase 1)
Diseases named in the same sentence as PON1 in open-access papers (continued):
Sharing a sentence is not in itself a finding about the gene and the disease.
atherosclerosis (continued). "PON1 reduces macrophage oxidation of LDL as well as macrophage oxidative stress, and increases cholesterol efflux from macrophages to high-density lipoprotein (HDL), thus reducing foam cell formation and, as a consequence, the development or progression of atherosclerosis." (PMID 25993297, 2015). "The special localization of PON1 in the HDL complex of human serum led to speculation that the enzyme plays also an important physiological role in lipid metabolism and that it protects against the development of atherosclerosis." (PMID 22824324, 2012). "Knockout mice lacking the PON1 gene develop atherosclerosis more rapidly than do wild-type mice." (PMID 21543280, 2011). "This seems to indicate that PON1 is not involved in the development of atherosclerosis by an impairment of endothelium-dependent vasomotion, but the exact mechanism remains unknown." (PMID 22214423, 2011). "PON1 is considered to protect against atherosclerosis, but it is unclear whether this relation is independent of its carrier, HDL." (PMID 19710913, 2009). "By modulating the oxidation of LDL, PON1 abolishes the oxidized LDL stimulated induction of monocyte-chemotactic protein-1 (MCP-1) production by endothelial cells, thereby preventing monocyte/endothelial cell interaction in one of the earliest processes of atherosclerosis." (PMID 18937674, 2008). "Thus, we proposed that MPO and PON1 may be involved in atherosclerosis by acting as proteins, rather than enzyme activities." (PMID 41704870, 2026). "However, whilst discovery of the key substrate(s) in the mechanism by which PON1 protects against atherosclerosis is essential for our understanding of its role, this may not be critical to make use of it clinically." (PMID 36873390, 2023). "Therefore, it can be concluded that lack of this enzyme or even reduced the activity of the PON1, could accelerate atherosclerosis and CVDs." (PMID 29118945, 2017). "This inverse association is, however, within the range which could be explained by publication bias, but it does not deny that the wider range of PON1 activities encountered in populations resulting from other genetic and acquired influences are relevant to the development of atherosclerosis." (PMID 26528181, 2015). "Since the atheroma formation was not evaluated in this study, we can speculate that unchanged PON1 activity and the lack of associations between PON1, LDL and LDLox levels are most likely because LDL levels evaluated in this study corresponded to early stages of atherosclerosis." (PMID 22721254, 2012). "Moreover, PON1 seems not play a role in early atherosclerosis, although it may play a role in a later stage of cardiovascular diseases." (PMID 22721254, 2012). "Instead, focus has shifted to the atherosclerosis-related aspects of HDL biology that are not reflected in HDL-C measurements, such as paraoxonase 1 (PON1) activity." (PMID 24330840, 2013). "Also, we only investigated ApoA1, PON1 and PON3 enzymes in liver cells; we did not consider other factors that are related to atherosclerosis in the liver or in other tissues such as endothelium and blood." (PMID 29215336, 2017). "Although the exact physiological role of PON1 has not been fully elucidated, it is widely accepted that its primary biological function in vivo is to prevent the lipid peroxidation of LDL and macrophage membranes, both of which may contribute to accelerated atherosclerosis." (PMID 39456469, 2024).
diabetes (156 papers, 2007 to 2026). "Our multivariate analysis further strengthens the case for TETRA and PON1 as potential biomarkers in heart failure, revealing their independent associations with HF severity even after adjusting for age, sex, diabetes, and LVEF." (PMID 40422267, 2025). "The relationship between them is mutual because polymorphism can be a reason for the installation of diabetes and after the onset, PON1 activity will be much lower." (PMID 38474211, 2024). "Studies suggest that low PON1 levels in diabetes are one of the causes of retinopathy and even nephropathy." (PMID 38474211, 2024). "Several different PON-1 polymorphisms have been identified in the Japanese population and have been linked to a differential risk for atherogenic dyslipidemia, diabetes, diabetic microvascular complications, stroke, and osteoporosis." (PMID 39765763, 2024). "Despite some case–control studies showing an association with ASCVD, particularly in younger people and diabetes, results have been inconsistent even in investigations where PON1 activity was clearly linked with ASCVD." (PMID 38887979, 2024). "PON1 polymorphisms were also studied in another Caucasian population with type 1 diabetes mellitus (T1DM), where it was found that genotypes LL on 55, AA (–162) and GG (–1074), were associated with an increased urinary albumin loss." (PMID 38982880, 2024). "Both ACTN3 R577X and PON1 T(-107)C polymorphisms are associated with nutritional status and blood glucose and lipid levels in women with diabetes/hypertense." (PMID 37948561, 2023). "The impression gained is that obesity is often associated with decreased PON1 activity, albeit most obviously when triglycerides are raised or diabetes is present." (PMID 36873390, 2023). "Based on these evidences, the present study aimed to analyze the associations between I/C ACE, R577X ACTN3 and T(-107)C PON1 polymorphisms and metabolic and anthropometric parameters in women with diabetes and hypertension." (PMID 37948561, 2023). "It has been reported that PON1 activity decreases with diabetes progression, in addition to being associated with dyslipidemia." (PMID 37948561, 2023). "The association of the PON1 gene with oxidative stress and diabetes had been reported in a T2D animal model." (PMID 35055468, 2022). "Due to its influence on oxidative stress and inflammation, the activity of the HDL-associated enzyme paraoxonase 1 (PON1) has been investigated in several pathological conditions, including vascular diseases, renal disease, diabetes, and cancer." (PMID 34881279, 2021). "In particular, the relationship between PON1 and diabetes is peculiar and reciprocal, with diabetes reducing PON1 levels on the one hand and the PON1 genotype being associated with the risk of diabetes development on the other." (PMID 34063950, 2021). "Specifically, PON1 overexpression in an experimental diabetes mouse model was associated with decreased macrophage-associated oxidative stress, decreased diabetes development and mortality." (PMID 34064071, 2021). "Since then numerous studies analyzing the relationship between PON1 promoter polymorphism and diabetes mellitus in different populations were conducted." (PMID 33670025, 2021). "PON1 is an HDL- associated anti-oxidant and reduced PON1 activity has been associated with diabetes and its cardiovascular complications." (PMID 34416903, 2021). "Another protein associated with HDL and known to be affected in diabetes is the anti-oxidant enzyme PON-1." (PMID 33375461, 2020). "Recent studies have shown that PON1 plays a protective role in other diseases that are associated with inflammation and oxidative stress, such as Type 1 and Type 2 Diabetes Mellitus and Non-Alcoholic Fatty Liver Disease." (PMID 31430977, 2019). "PON1 paraoxonase activity was associated with diabetes and positive medical history of CHD independently of other factors." (PMID 30935088, 2019).
diabetes (continued). "We noted association of diabetes and PON1 paraoxonase activity, which is considered as highly dependent on genetic factors." (PMID 30935088, 2019). "In multivariate analysis, PON1 paraoxonase activity was independently of confounding factors associated with diabetes (OR = 0.985; p = 0.024) and premature CHD in family history (OR = 0.983; p = 0.027)." (PMID 30935088, 2019). "Many studies have examined the associations between paraoxonase‐1 (PON1) genetic polymorphisms (Q192R, rs662 and L55M, rs854560) and the susceptibility to type 2 diabetes mellitus (T2DM) across different ethnic populations." (PMID 29314660, 2018). "HDL-associated PON-1 is low in patients with diabetes mellitus and leads to dysfunctional HDL with impaired antioxidant capacity." (PMID 30286142, 2018). "The major discovery of this present study is that we identified glycation of PON1 as a risk factor of endothelial dysfunction in diabetes." (PMID 28374834, 2017). "The combined effects led to prevention of low-density lipoprotein (LDL) oxidation, which can be associated with an increase in HDL levels and paraoxonase 1 (PON1) activity, thereby lowering these cardiovascular risk factors in diabetes." (PMID 28333071, 2017). "Taking these data together, it demonstrates that PON1 glycation is an inducer of ER stress and a risk factor of endothelial dysfunction in diabetes." (PMID 28374834, 2017). "In assessment of association between CAD and diabetes in Iranian population the following genes showed significant association: paraoxonase 1, adiponectin, eNOS, CETP, AT1R, resistin, MMP-3, BChE K, Apo E, ACE." (PMID 26587547, 2015). "A number of medical conditions including diabetes mellitus, chronic kidney disease, familial hypercholesterolaemia and inflammatory arthritides are associated with both decreased serum PON1 activity and increased CVD risk." (PMID 26528181, 2015). "The aim of this work is to investigate PON1 Q192R and L55M polymorphisms in Egyptian patients with type 2 diabetes mellitus (T2DM) and its association with CVD." (PMID 25551104, 2014). "In conclusion, we have shown that the Q192R polymorphism is a determinant of both PON1 concentration and activity and this association appeared to be enhanced in subjects with diabetes." (PMID 25477710, 2014). "This association appeared to be enhanced in subjects with diabetes, thus suggesting a need to adjust for potential genetic confounding in future PON1 studies, involving diabetic subjects." (PMID 25477710, 2014). "In the presence of diabetes, PON1-192RR genotype associated with an increased risk of SCS while 55MM genotype associated with lower risk." (PMID 25551104, 2014). "There was indication that the effect of the variant on PON1 concentration was more important in participants with diabetes." (PMID 25477710, 2014). "While PON1 concentration associated negatively with Caucasian ethnicity and duration of diabetes, and positively with 192R allele." (PMID 25551104, 2014). "In this work, we investigated PON1 Q192R and L55M polymorphisms in Egyptian patients with type 2 diabetes mellitus (T2DM) and its association with CVD." (PMID 25551104, 2014). "An association between PON1 polymorphisms and cardiovascular disease has been found, and a variant of the PON1 gene is associated with diabetic retinopathy in insulin-dependent diabetes mellitus." (PMID 23441121, 2013). "After adjusting for gender, hypertension, fibrinogen, and frequency of diabetes, the PON1 55 LL genotype was found to be associated with an increased risk of RVO (β=1.755; OR=5.783; p<0.001; 95% CI=2.579–12.967)." (PMID 23441121, 2013). "Several recent studies have suggested that PON1 concentration decreases in some inflammatory and ischemic diseases, such as diabetes and acute pancreatitis, which are associated with an increase in oxidative stress." (PMID 23197980, 2012). "PON1 activity has also been linked to a number of other health-related phenotypes in addition to vascular disease and diabetes." (PMID 22685667, 2012).
diabetes (continued). "Stage 3 chronic renal disease, defined as cystatin C-based estimated glomerular filtration rate (eGFR) less than 60, was associated with lower PON1 mass in subjects with diabetes." (PMID 22701797, 2012). "Differences in PON1 between subjects have been shown to be due to genetic polymorphisms, presence of diabetes, presence of hepatic disease, and presence of renal disease." (PMID 22701797, 2012). "Recent findings have demonstrated that consumption of PJ by patients with diabetes decreases oxidative stress in their serum and contributes to PON1 stabilization, increases PON1 association with HDL, and stimulates the enzyme catalytic activities." (PMID 23497651, 2012). "More recently, certain PON1 polymorphic variants were implicated as risk factors for other chronic inflammatory diseases, including RA and types 1 and 2 diabetes." (PMID 22044644, 2011). "Patients with diabetes who received 240 mL of cranberry juice for 12 weeks showed lower serum glucose levels and improved levels of cardiovascular risk markers (apoB, apoA-1, and Paraoxonase-1)." (PMID 38752013, 2024). "However, based on the number of studied patients in this region, it seems that a general panel of NOS, TCF7L2, VDR, and PON1 polymorphisms can be used as diagnostic panel markers to identify the susceptible cases to diabetes in Middle East population." (PMID 35366956, 2022). "Accordingly, it was suggested that, as a state of increased oxidative stress, diabetes may cause the antioxidant activity of the PON-1 enzyme to diminish." (PMID 36463116, 2022). "Additionally, in people with CVD and diabetes, it is reported that carriers of the −162A allele have higher PON1 activity than −162G." (PMID 35453382, 2022). "Furthermore, PON-1 has been shown to be a protective factor in disease associated with inflammation and oxidation, such as diabetes mellitus and non-alcoholic fatty liver diseases." (PMID 36422550, 2022). "Low PON-1 activity has been associated with increased risk of major cardiovascular events, with many diseases characterized by a large inflammatory component (i.e., diabetes mellitus, rheumatoid arthritis, systemic lupus erythematosus, etc.)." (PMID 34945250, 2021). "Low levels of PON1 have been associated with hypercholesterolemia, diabetes, and vascular diseases." (PMID 34684678, 2021). "Taken together, those reports and current results indicate that HDL quality with PON-1 activity and particle size may be helpful for better understanding of COVID-19 risk and underlying disease, such as hypertension, diabetes, and coronary heart disease." (PMID 33535459, 2021). "The contradictory results might be explained by PON1 genetic polymorphism, which may determine the variable role of PON1 in diabetes." (PMID 32872672, 2020). "Hence, it is necessary to have a good understanding of the kinetics parameters of PON1 and catalase to predict their diagnostic relevance as a biomarker in diabetes and to study the effects of treatment with M. oleifera extract." (PMID 32911700, 2020). "Be this as it may, and independently of genotype, low activity of serum PON1, has been reported with oxidative stress conditions associated with uncontrolled diabetes and cardiovascular complications." (PMID 32911700, 2020). "Recently, it was stated that PON1 is linked to a reduction in oxidative stress and inflammation, and it has already been clearly linked to several diseases that express high levels of inflammation such as diabetes mellitus." (PMID 31847187, 2019). "Examining the role of genetic polymorphisms of PON1 in the Sudanese diabetes and how they might impact CHD complications among patients is strongly recommended." (PMID 31372141, 2019). "There were significant association between PON1 and period of diabetes in T1DM and T2DM." (PMID 31372141, 2019).
diabetes (continued). "Multiple logistic regression was used to evaluate whether PON1 activity was associated with outcomes (family history of cardiac episode or diabetes mellitus) independently of other confounders." (PMID 30935088, 2019). "In perspectives, PON1 glycation is a risk factor of endothelial dysfunction in diabetes." (PMID 28374834, 2017). "Also, the risk factors for CAD (diabetes, hypertension, dyslipidemia) were significantly associated with PON1 RR genotype." (PMID 25551104, 2014). "Furthermore, PON1 QQ192 genotype was associated with increased PON1 concentration especially in subjects with diabetes." (PMID 25477710, 2014). "The Q192 was significantly associated with 5.8 units' increase in PON1 concentration and 15.4 units' decrease in PONase activity after adjustment for age, sex, BMI, and diabetes, with suggestion of differential effects by diabetes status." (PMID 25477710, 2014). "Taken together, our results show that the R allele increases PON1 activity but also indicate that the PON1 QQ192 may be important in individuals with increased oxidative stress such as diabetes even though it suppresses the activity of the enzyme." (PMID 25477710, 2014). "Paraoxonase 1 is cardioprotective due to its antioxidant activity associated with high-density lipoprotein and is hypothesized to be protective against diabetes." (PMID 23894450, 2013). "We did not obtain any prevalence of the presence of risk factors such as arterial hypertension (p = 0.955), diabetes mellitus (p = 0.847), overweight/obesity (p = 0.723), smoking (current/ex-smokers, p = 0.914), familial predisposition (p = 0.141) between patients with different PON1 L55M genotypes." (PMID 36547064, 2022). "Furthermore, in patients with diabetes significantly higher levels of oxidized LDL (Ox-LDL) in relation to apoB concentration (Ox-LDL/apoB ratio) were attributable to the -108 TT genotype associated with lower PON1 in comparison with the CT or CC genotypes." (PMID 33670025, 2021). "Additionally, we found that PON1 paraoxonase activity is independently associated with diabetes." (PMID 30935088, 2019). "We carried out this meta‐analysis to explore the influence of paraoxonase 1 activity on the susceptibility of diabetes mellitus (DM), diabetic macroangiopathy and diabetic microangiopathy." (PMID 29981194, 2018). "Interestingly, the lower PON1 paraoxonase activity in the ACS patients was inversely correlated with the number of concomitant CVD risk factors (diabetes, hypertension, obesity, smoking, excessive alcohol consumption, and family history of CVD (r = 0.57, p<0.0001)." (PMID 26241956, 2015). "Finally, diabetes is associated with both reduced PON1 activity and PON1 genotypes." (PMID 22685667, 2012). "Studies have shown that resveratrol significantly reduces retinal inflammation and oxidative damage by modulating paraoxonase 1 (PON1), a key regulator of microvascular complications in diabetes." (PMID 40218965, 2025). "Decreases in paraoxonase 1 activity have also been observed in patients with diabetes mellitus and myocardial infarction." (PMID 40362292, 2025). "Within the CAE group, PON1 activity levels were compared across subgroups based on sex, smoking and alcohol use, hypertension, diabetes status, number of ectatic vessels, and Markis classification." (PMID 40342642, 2025). "In human medicine, reduced PON-1 activity has been documented in several disorders associated with oxidative stress, including cardiovascular diseases, chronic kidney disease (CKD), diabetes mellitus, chronic liver failure, and pancreatitis." (PMID 41295705, 2025). "Predictor variables included TETRA, PON1, age, sex, diabetes status, and left ventricular ejection fraction (LVEF), selected based on their significant differences across groups and their established evidence from the HF literature." (PMID 40422267, 2025).